TLR4 (toll like receptor 4)
Diseases named in the same sentence as TLR4 in open-access papers (continued):
Sharing a sentence is not in itself a finding about the gene and the disease.
acute pancreatitis (continued). "In acute pancreatitis, 15d-PGJ2 also attenuates the expression of TLR4 in acinar cells and inflammatory responses and reduces the severity of acute pancreatitis." (PMID 31467514, 2019). "It is noteworthy that TLR4 expression was increased in pancreatic acinar cell after acute pancreatitis induced by caerulein injections or by taurocholate infusion." (PMID 30577532, 2018). "Another therapeutic approach was the administration of lornoxicam in acute pancreatitis patients, who presented reduced mortality associated with reduced TLR2 and TLR4 mRNA levels in the peripheral blood mononuclear cells." (PMID 26347203, 2015). "CO has been shown to modulate TLR4 responses in acute pancreatitis and possibly responses to heme in sickle mice." (PMID 24860503, 2014). "As hyaluronan has been shown to be accumulated in the edematous interstium during acute pancreatitis, this could lead to the activation of TLR4 in endothelial cells further contributing to inflammation and immune cell recruitment to the pancreas." (PMID 38585277, 2024). "In this review we will address the various mechanisms mediated by TLR4 in the advancement of acute pancreatitis and how targeting this receptor could lead to improved outcomes for patients suffering from this condition." (PMID 38585277, 2024). "TLR4 plays a key role in the inflammation of endothelial cells, which could contribute to the infiltration of immune cells during the progression of acute pancreatitis." (PMID 38585277, 2024). "Because of the diversity of roles TLR4 plays in the progression of pancreatitis and pancreas damage, the inhibition of TLR4 could be worth investigating for the treatment of acute pancreatitis in humans." (PMID 38585277, 2024). "Pretreatment of daphnetin at 4 mg/kg significantly blocks the TLR4/NF-κB signaling pathway by inhibiting the phosphorylation of IκBα and the expression of TLR4, thereby attenuating pancreatic injury in rat severe acute pancreatitis (SAP) model compared to the control group." (PMID 39011506, 2024). "However, TLR4 signaling has proven to play a significant role in acinar cell inflammation during acute pancreatitis, which will be discussed in a later section." (PMID 38585277, 2024). "Interestingly, high-fat diets specifically increase the expression of intestinal TLR4, and exacerbate intestinal barrier dysfunction in a TLR4-dependent manner in rats with severe acute pancreatitis." (PMID 34814947, 2021). "The results of the study could provide a good connection between high-fat diet and TLR4-mediated necroptosis for the pathophysiology of acute pancreatitis." (PMID 31998444, 2020). "During experimentally induced systemic inflammatory conditions (e.g., acute pancreatitis and acute hepatitis) Lac may downregulate Toll-like receptor 4, NLRP3 (NACHT, LRR, and PYD domains-containing protein 3) inflammasome, and concomitantly IL-1β." (PMID 28499395, 2017). "Furthermore, the direct proinflammatory role of TLR4 in the progression of caerulein or L-arginine-induced acute pancreatitis was demonstrated independently of LPS by the genetic deletion of TLR4." (PMID 26347203, 2015). "PPT-A gene deletion regulates H2S-induced TLR 4 signaling pathway in caerulein-treated pancreatic acinar cells, suggesting that in acute pancreatitis, H2S may upregulate the TLR4 pathway and NF-κB via substance P." (PMID 24278674, 2012). "Therefore, indirectly decreasing NF-κB signaling through inhibition of TLR4 could result in beneficial outcomes in the study of acute pancreatitis." (PMID 38585277, 2024). "The production of HMGB1 and its signaling through TLR4 has been shown to be especially important in the progression of severe acute pancreatitis as administration of HMGB1 to mice resulted in increased pancreatic injury and NF-ΚB signaling that could be attenuated in TLR4-deficient mice." (PMID 38585277, 2024).
acute pancreatitis (continued). "Taken together, not only could inhibition of TLR4 affect immune infiltration and damage within the pancreas during the onset of acute pancreatitis, but inhibition of TLR4 could also alleviate remote organ complications during severe acute pancreatitis such as adult respiratory distress syndrome." (PMID 38585277, 2024). "Therefore, CO-HbV may decrease the pathogenesis of acute pancreatitis through the HMGB1/TLR-4 pathway." (PMID 29847178, 2018). "In severe acute pancreatitis rats with acute lung injury, notoginsenoside R1 promotes TOLLIP expression by inhibiting miR-128-2-5p, thereby inhibiting the expression of TLR4, MyD88, and NF-κB related pathway proteins and exerting a protective effect." (PMID 39735680, 2025). "Cholesterol has the potential to induce inflammation by activating pathways such as TLR4, NLRP3, and NETs, indicating its vital role in the pathogenesis of acute pancreatitis." (PMID 38374155, 2024). "In vivo TLR4-/- and CD14-/- mice showed reduced acinar atrophy in a severe acute pancreatitis model." (PMID 38585277, 2024). "Not only are NETs produced directly through TLR4 signaling, but NET release is also supported by cytokines produced in other tissues during the progression of acute pancreatitis." (PMID 38585277, 2024). "A previous study reported that DAP reduced Toll-like receptor-4 (TLR4) expression and suppressed the activation of the NF-κB signaling pathway in acute pancreatitis showing its potential to avert pancreatitis." (PMID 36249766, 2022). "The treatment with S. miltiorrhiza inhibited ICAM-1, toll like receptor-4 (TLR-4) and NF-κβ in rats with severe acute pancreatitis." (PMID 29163178, 2017). "Use of PPAR-α agonist reduced inflammation and severity in acute pancreatitis via repression of TLR2 and TLR4 mRNA." (PMID 26347203, 2015). "Genetic deletion and pharmacologic antagonism have demonstrated that specific DAMP receptors, including Toll-like receptors TLR4 and TLR9, are also required for inflammation in experimental acute pancreatitis." (PMID 26347203, 2015). "Another study found that TLR4-positive acinar cells respond to LPS by activating the inflammasome and producing TNF-α, IL-6, IL-10, IL-1β, IL-18, and MCP-1 during acute pancreatitis, and these effects could be exacerbated by alcohol." (PMID 38585277, 2024). "Specifically, the absence of TLR4 expression in intestinal epithelial cells exacerbates pancreatic and intestinal damage during acute pancreatitis." (PMID 38374155, 2024). "Toll-like receptor 4 (TLR4) is a pattern recognition receptor that has been noted to respond to endogenous ligands such as high mobility group box 1 (HMGB1) protein and or exogenous ligands such as lipopolysaccharide both of which can be present during the progression of acute pancreatitis." (PMID 38585277, 2024). "Similarly, TLR4 and NOD1 knockdown mice are protected from acute pancreatitis." (PMID 26347203, 2015). "Furthermore, we have shown that PPTA deficiency and blockage of H2S synthesis may play an important role that can regulate the toll-like receptor 4 (TLR4) pathway and subsequent innate immune response in acute pancreatitis, implying an interaction between SP/H2S occurs via TLR4 and NF-kB pathway." (PMID 24278674, 2012).
allergic asthma (34 papers, 2007 to 2026). A asthma with a basis in a pathological type I hypersensitivity reaction. "There is scarce information from the relationship of these proteins and treatments, but it recently has been demonstrated in an allergic asthma rat model the role of AIT inhibiting the HMGB1/TLR4/NF-κB signaling, in agreement with our data." (PMID 40650018, 2025). "Other authors have demonstrated that the stimulation of TLR-4/(Nf)-kB is involved in the development of allergic asthma in various murine models." (PMID 41049431, 2025). "Our study highlights that S100A8 and S100A9 play critical roles in the pathogenesis of allergic asthma by promoting macrophage perturbation and glycolysis through the TLR4/MyD88/NF-κB signaling pathway." (PMID 38646478, 2024). "CycloZ markedly reduced these allergic responses and significantly downregulated the TLR4 pathway, suggesting dual action in reducing inflammation and suppressing the initial immune triggers involved in allergic asthma." (PMID 39682780, 2024). "CycloZ bridges this gap by dual mechanisms: it mitigates TLR4-driven immune triggers of allergic asthma and reduces downstream Th2-mediated inflammation, notably decreasing cytokines like IL-4 and IL-13." (PMID 39682780, 2024). "S100A8 and S100A9 play critical roles in allergic asthma pathogenesis by promoting macrophage perturbation and glycolysis through the TLR4/MyD88/NF-κB signaling pathway." (PMID 38646478, 2024). "Stimulation of TLR4 trough Der p2 induces IgE secretion and an inflammatory response characterized by eosinophils and lymphocytes in experimental allergic asthma." (PMID 33114004, 2020). "To confirm if TLR signaling had a protective role in our mouse model, we established OVA-induced allergic asthma in tlr2−/−, tlr4−/−, and tlr9−/− mice, and WT mice were used as the control." (PMID 30510553, 2018). "The present study was designed to evaluate the effect of concomitant TLR3 and TLR4 stimulation in a murine model of allergic asthma." (PMID 26494305, 2015). "These relations are substantiated by studies in animal model showing that TLR2 and TLR4 microbial ligands LPS or LTA modulate experimental allergic asthma." (PMID 24098413, 2013). "Several epidemiological analyses have highlighted positive associations between TLR2, TLR4 and CD14 (TLR4s co-receptor) gene polymorphisms and allergic asthma susceptibility in human." (PMID 24098413, 2013). "Since LPS has been implicated in the regulation of allergic asthma development mainly through TLR-4 signalling pathway, we studied the effect of A. baumannii administration on allergic responses in TLR4−/− mice." (PMID 21789200, 2011). "Moreover, several studies revealed that there are positive correlations of TLR2 and TLR4 with allergic asthma." (PMID 36012669, 2022). "When looking at the cumulative score, the same combination of proteins (AKT1, STAT1, MAPK13, and TLR4) triggered 89.27% of the non-allergic asthma effector proteins and inclusion of the rest of proteins of interest would not substantially increase this percentage." (PMID 33936056, 2021). "Additionally, a recent study investigating allergic asthma shows that TLR-4/LPS signaling modulates a leukotriene B4 receptor-2-mediated cascade in mast cells resulting in the release of the Th2 cytokine IL-1337." (PMID 31316085, 2019). "In our study, although tlr2−/−, tlr4−/−, and tlr9−/− mice all displayed more severe disease compared with WT mice after allergic asthma establishment, the parameters of allergic symptom, including total cell number, the number of eosinophil and IgE level, in these mice displayed difference." (PMID 30510553, 2018). "Finally it has been proposed that HDM extract can distinctly trigger allergic rhinitis through the β-glucan TLR2 dependent activation of the upper airways or allergic asthma through the LPS-induced TLR4 activation of the lower airways." (PMID 24098413, 2013).
allergic asthma (continued). "A Der p 2 + LPS airway sensitization model triggered experimental allergic asthma in wild type and MD-2-deficient, but not TLR4-deficient mice, clearly confirming that Der p 2 can transport LPS to TLR4." (PMID 23724247, 2013). "Helicobacter pylori upregulate Toll-like receptor 4 (TLR4), and although results are complex, human and murine studies suggest that activation of TLR4 may be protective against allergic asthma." (PMID 19112508, 2008). "Study in allergic asthma mice and MHS alveolar macrophages further demonstrate that the damage-associated molecular pattern S100A8/A9 enhances glycolysis and lactate production via TLR4/MyD88/NF-κB signaling, concomitant with increased ACLY phosphorylation and upregulation of M1 signature factors." (PMID 41602451, 2026). "Thus, we concluded that MUC5AC expression is regulated by sNASP/TRAF6 signaling via TLR2 and TLR4, which may provide a novel therapeutic strategy for allergic asthma." (PMID 36012669, 2022). "For instance, in an experimental allergic asthma model, an association between TLR4 and allergen-induced inflammation was found, as mice lacking a functional TLR4 pathway developed a reduced Th2 immune response with lower circulating ovalbumin-specific IgE levels in comparison to WT mice." (PMID 35386993, 2021). "In an allergic asthma model, calprotectin S100A8/A9 drives M1 polarization via the TLR4/MyD88/NF κB axis and markedly augments glycolysis, as indicated by raised lactate and glycolytic enzymes." (PMID 41602451, 2026). "The LPS–TLR4–epithelium pathway has already been described in a murine model for allergic asthma with HDM, making TLR4 and its signalling pathways another target for the next experiments and possible treatment options." (PMID 35371094, 2022). "Results of the triggering analysis performed over allergic asthma revealed that STAT1, MAPK13, and TLR4 are the top genes that play a trigger role according to the individual score." (PMID 33936056, 2021). "In an allergic asthma model, BPE-induced airway inflammation was demonstrated to be dependent on TLR4, influencing immune cell infiltration and the local production of IL-4 and IL-10 cytokines, without affecting airway hyperresponsiveness (AHR)." (PMID 35386993, 2021). "LPS, a TLR4 agonist, served as a control to validate the therapeutic effect of miR-146a mimic in the OVA-induced allergic asthma model." (PMID 32600285, 2020). "Previous studies have revealed an increased PLA2 activity due to the stimulation of Toll-like-receptor-4 and other receptors that are triggered upon allergen exposure, such as HDM, in allergic asthma." (PMID 30658644, 2019). "It has been shown that LPS exposure or triggering of TLR4 reduces AAI and allergic asthma by suppressing Th2 cell stimulation by DC." (PMID 27483441, 2016). "We tested the effect of agonists of TLR2 (P40 protein of Klebsiella pneumoniae and the Pam3Cys lipopeptide), TLR3 (double-stranded RNAs Poly(I∶C)), TLR4 (LPS and lipid A) and TLR7 (R848) on experimental allergic asthma and autoimmune diabetes in the NOD mouse." (PMID 20628601, 2010). "While both 3′SL and 6′SL indeed are known to modify mucosal immunity via TLR4 interaction, this present study clearly demonstrated differences in immunological outcomes in mice fed a 3′SL or 6′SL containing diet in this HDM-induced acute allergic asthma model." (PMID 41404114, 2025). "The TLR4/MyD88/TRIF/NF-κB signaling pathway and ACLY activity were inhibited in OVA-induced MH-S cells with knockdown of S100A8 or S100A9 and allergic asthma mice, suggesting that knockdown of S100A8 or S100A9 inhibits glycolysis by suppressing the TLR4/MyD88/TRIF/NF-κB signaling pathway." (PMID 38646478, 2024). "Compared with WT mice, tlr2−/−, tlr4−/− but not tlr9−/− mice exhibited increased infiltration of eosinophils in alveoli after allergic asthma establishment." (PMID 30510553, 2018).
allergic asthma (continued). "In contrast, LPS, rather than β-glucans, was critical for HDM-induced TLR4-dependent innate immunity in lung mucosa and allergic asthma." (PMID 23724247, 2013). "Furthermore, several studies concerning the direct sensitization of HDM have indicated that various factors, such as IL-21 from CD4+ T cells, IL-33 from inflammatory monocytes, TLR4-dependent inflammation, and IRF3 signals, participate in mouse models of allergic asthma." (PMID 31616416, 2019).
hyperlipidemia (34 papers, 2011 to 2026). "Recent studies showed an association between the increase in TLR4 levels and an increase in lipid levels, which suggests that TLR4 are important in hyperlipidemia." (PMID 32089647, 2020). "In conclusion, HSYA alleviated myocardial inflammatory injury through suppressing TLR4, offering an alternative medication for MI/R associated with hyperlipidemia." (PMID 27731393, 2016). "HSYA administration suppressed the over-expression of TLR4 and alleviated heart damage caused by MI/R complicated with hyperlipidemia." (PMID 27731393, 2016). "High-fat diet-induced hyperlipidemia exaggerated the outcomes of myocardial I/R in rats through inflammatory response and HSYA could relieve the cardiac injury caused by MI/R+hyperlipidemia through suppressing TLR4 in vivo and in vitro." (PMID 27731393, 2016). "Interestingly, the TLR4 signaling has been reported to be associated with Myf5 expression suggesting the association between pro-inflammatory milieu following the hyperlipidemia and/or intimal lipid burden with subsequent mobilization/activation of SMCs via Myf5." (PMID 35531433, 2022). "Hyperlipidemia induced by HFDs has been shown to stimulate inflammatory signaling pathways, such as toll-like receptor 4 (TLR4) and nuclear factor kappa-B (NF-κB)." (PMID 40612305, 2025). "The knockout of the TLR4 gene significantly alleviated the overweight and hyperlipidemia/hypoglycemic syndromes in mice, which confirmed that TLR4 plays an important role in glycolipid metabolism." (PMID 38275739, 2024). "• Suppressing hyperlipidemia;• Suppressing oxidative stress;• Enhancing insulin sensitivity;• Regulating intestinal barrier function;• Suppressing TLR4-related inflammation response;• Enhancing autophagy;• Suppressing cell apoptosis." (PMID 34414181, 2021). "Toll-like receptor 4 (TLR4) is an important modulator of innate immunity which is associated with innate immunity and metabolic disorders including hyperlipidemia; TLR4 is essential for inflammation development." (PMID 32089647, 2020). "Recent evidence suggested that hyperlipidemia was able to modulate TLR4 activation and contribute to the increased TLR4 expression." (PMID 33426065, 2020). "This suggests that, in the context of prenatal inflammatory stimulation, TLR4 is overactivated to compensate for the loss of TLR2, which likely contributes to the more severe hyperlipidemia phenotype in TLR2-deficient offspring-pLPS." (PMID 31507457, 2019). "Taken together, our results revealed that hyperlipidemia augmented MI/R injury through LPS combining with TLR4." (PMID 27731393, 2016). "Briefly, hyperlipidemia/FFAs activate TLR4, resulting in the phosphorylation of c-Src and then EGFR in c-Src/EGFR complex and subsequent activation of AKT and ERK." (PMID 27014908, 2016). "We also found that hyperlipidemia+MI/R group owned significantly higher TLR4 level in hearts than MI/R group." (PMID 27731393, 2016). "Our results also showed that HSYA failed to ameliorate cardiac injury and inflammatory response under the condition of TLR4-deficiency, which proved that HSYA restored cardiac injury induced by hyperlipidemia+MI/R through suppressing TLR4." (PMID 27731393, 2016). "In our study, serum LPS level and myocardial TLR4 expression level were increased in response to MI/R+hyperlipidemia." (PMID 27731393, 2016). "In order to test how HSYA ameliorated cardiac injury induced by hyperlipidemia+MI/R, TLR4-KO mice were applied." (PMID 27731393, 2016). "HSYA also suppressed the over-expression of TLR4 in hearts induced by I/R combined with hyperlipidemia." (PMID 27731393, 2016). "The results showed that HSYA inhibited hyperlipidemia induced excessive LPS release, suppressed TLR4, depressed inflammatory response, and alleviated MI/R injury in vivo." (PMID 27731393, 2016). "TLR4 expression has been increased in human macrophages in lipid-rich plaques, indicating TLR4 activation by hyperlipidemia." (PMID 25372283, 2014).